GLI1 (GLI family zinc finger 1)
Diseases named in the same sentence as GLI1 in open-access papers (continued):
Sharing a sentence is not in itself a finding about the gene and the disease.
basal cell carcinoma (continued). "Despite widespread expression of GLI1 in tumors, considered to be a marker of HH activation, HH inhibitors have solely been granted FDA approval for the treatment of advanced basal cell carcinoma of the skin, a type of tumor that bears activating mutations of the HH pathway." (PMID 32879407, 2020). "Clinical studies have also demonstrated that the expression of Gli1 can be utilized as a potential maker and imply poor prognosis in lung squamous cell carcinoma, basal cell carcinoma, head and neck squamous carcinoma which indicting the potential prognostic value of Gli1." (PMID 29113369, 2017). "Since GLI1 has been shown to drive expression of FOXM1 in basal cell carcinoma, there is an appealing logic to the hypothesis that EWS/FLI1 indirectly targets FOXM1 through deregulation of GLI1." (PMID 23365673, 2013). "Reports have shown that FOXM1 is transcriptionally regulated by Gli1 in basal cell carcinomas; however, whether FOXM1 is regulated at the protein level has not been reported." (PMID 23229761, 2013). "Transgenic over-expression of Gli1 in mice leads to the development of basal cell carcinoma." (PMID 22768056, 2012). "For instance, the Gli1 gene is amplified in human glioma and activated in basal cell carcinoma." (PMID 22768056, 2012). "Gli-3 also inhibits Gli-1's ability to upregulate bcl-2 transcription in basal cell carcinoma." (PMID 17505514, 2007). "Interestingly, the tumor with the highest level of GLI1 expression (tumor ID TCGA-AA-3715) harbored a missense mutation in PTCH1 (P681L; c.2042C>T) that was identical to a confirmed somatic alteration previously identified in a basal cell carcinoma." (PMID 24368541, 2013). "For example, in basal cell carcinoma, nuclear localisation of SMO via a nuclear/nucleolar localisation signal activates GLI1 independently of canonical SMO inhibitors, explaining resistance in ~80% of patients." (PMID 40426308, 2025). "Atypical protein kinase C iota/lambda (aPKC) has been identified as a novel regulator of GLI, and like the VEGF/NRP2 pathway, results in a positive feedback loop enhancing GLI1 overexpression in basal cell carcinoma and has been also observed in drosophila." (PMID 34113570, 2021). "In basal cell carcinomas (BCC), atypical protein kinase C ι/λ (aPKC) positively regulates Gli1 by phosphorylating two serine/threonine residues S243 and T304, which strengthens GLI1 DNA binding." (PMID 30754706, 2019). "The results of the present study also showed that the expression of GLI1, SHH, and PTCH1 involved in the basal cell carcinoma pathway was up-regulated in short-hair rabbits." (PMID 30770723, 2019). "While information is limited about retinoid regulation of GLI1 in OSCC, RA has been shown to reduce GLI1 activity in murine keratinocytes and basal cell carcinoma." (PMID 30978209, 2019). "In basal cell carcinoma, FOXM1 expression has been shown to be dependent on GLI1, the transcriptional effector of the Hedgehog-GLI pathway." (PMID 23365673, 2013). "In mice, overexpression of SHH, activates SMO, GLI1 or GLI2 and promotes development of basal cell carcinoma like tumors." (PMID 23342114, 2013). "Downstream targets of GLI1 signalling include molecules with regulatory effects on cell cycle and apoptosis such as Cyclin D2 or FOXM1 in basal cell carcinomas." (PMID 19706168, 2009). "Shh signaling, driven exclusively by PTCH1 that is SMO/GLI1-independent, includes induction of apoptosis in endothelial and neuroepithelial cells and regulation of the Cyclin B1/CDK1 pathway in basal cell carcinoma." (PMID 26545965, 2015).
basal cell carcinoma (continued). "Exon-specific differences observed for GLI1 in the discovery cohort were consistent with previously reported alternative transcription of this gene in basal cell carcinoma and the lack of detection in previous studies performed on previous HNSCC array studies." (PMID 24223768, 2013). "Consistent with a major role in carcinogenesis highly increased levels of GLI1 expression were found in basal cell carcinomas but not in the surrounding normal breast tissues." (PMID 19706168, 2009). "Also, a nuclear localization of SMO, which drives GLI1 activation and is unresponsive to SMO inhibitors, has been reported to occur in Ptch1-silenced Basal Cell Carcinoma cells, again suggesting the activity of alternative non-canonical Hh-signaling." (PMID 31873117, 2019).
colon carcinoma (56 papers, 2010 to 2025). "Dysregulation of Hh signaling contributed to gene mutation, metastasis, and angiogenesis in colon cancer, and termination of Hh signaling through GLI1 inhibition resulted in the inhibition of proliferation in colon cancer." (PMID 30423843, 2018). "Hedgehog/Gli1 signaling is implicated to be important in the maintenance of colon tumor." (PMID 25386960, 2014). "When the Hh pathway was inhibited in HT29 cells with the SMO inhibitor cyclopamine, reduced expression of stemness markers, such as CD44 and CD133, was observed, suggesting that Prdx2 may promote CSC-associated properties in colon cancer via the Hh/Gli1 signaling pathway." (PMID 27894099, 2016). "Lastly, TMED9 was shown to mediate colon cancer metastases by activating the GLI1, CNIH4 and TGFA regulatory pathway and opposing TMED3-WNT-TCF signaling." (PMID 40497947, 2025). "In the other, Omomyc downregulates GLI1, a transcription factor responsible for inducing metastatic and stem-like phenotypes in colon carcinoma cell lines." (PMID 36860495, 2022). "GLI1 expression has been used as a potential prognostic factor for survival in bladder and colon cancer." (PMID 33494284, 2021). "In this study, we focused on the role of GLI1 in the context of LTC4/CysLT2R signalling in colon cancer." (PMID 32814764, 2020). "In this study, the promotion of differentiation in colon cancer cells was found to occur via the inhibition of canonical Hh/GLI1 signalling." (PMID 32814764, 2020). "In cells obtained from mouse intestine and colon cancer patients, we identified GLI1 as a downstream regulator of 15-PGDH-induced redifferentiation." (PMID 32814764, 2020). "Treatment with cyclopamine showed a reduction in colon cancer progression and metastasis, and inhibition of Hh signaling through GLI1-targeted shRNA consistently displayed dramatically lower colony forming ability in colon CSCs." (PMID 30423843, 2018). "Dual targeting of Wnt/b-catenin and Hh-GLI1 signaling resulted in a better elimination of colon cancer cells compared with inhibition of GLI1 alone." (PMID 30423843, 2018). "Beta-catenin can negatively regulate Gli3 and positively regulate Gli1 independently of TCF in colon carcinoma CD133+ stem cell populations." (PMID 27999207, 2017). "Enhanced Gli1 levels were determined to drive the transition of colon carcinomas to a reprogrammed, embryonic stem cell-like, metastatic state and the Wnt/TCF pathway was suppressed." (PMID 27999207, 2017). "Inhibition of GLI1/GLI2 by GANT61 or expression of the repressor GLI3 down-regulated the expression of NER-related genes in the human colon carcinoma HT29 cell line." (PMID 26197339, 2015). "We have demonstrated rapid inhibition of GLI1 and GLI2 binding to target gene promoters (1 hr), reduced reporter activity specific to GLI-luciferase, and rapid inhibition of gene transcription in human colon carcinoma cell lines." (PMID 24962990, 2014). "The HT-29 cells were the second most sensitive to cyclopamine from the three colon cancer cell lines; the GLI1 levels were decreased by 36.4% (P<0.05) after 72 h." (PMID 25295109, 2014). "When the colon cancer cells were treated with cyclopamine, changes were observed in the GLI1 levels between the cell lines." (PMID 25295109, 2014). "When the colon cancer cells were treated with celecoxib, changes in the GLI1 levels in the three cell lines were evident." (PMID 25295109, 2014). "Mazumdar and colleagues demonstrated that inhibition of Gli1 using small molecule inhibitors induces double strand DNA breaks (DSBs) coupled with reduced DNA repair in colon cancer." (PMID 24926795, 2014). "GLI1 and GLI2 are constitutively activated in colon cancer cells by oncogenic signaling pathways upstream of GLI." (PMID 24962990, 2014). "Further, hTERT promoter activity was significantly elevated in human colon cancer cells stably over-expressing GLI1 or GLI2." (PMID 24086482, 2013).
colon carcinoma (continued). "Forced expression of GLI1 or a constitutively active mutant of GLI2 expression increased hTERT mRNA and protein in human colon cancer cells demonstrating HH/GLI-mediated regulation of hTERT expression." (PMID 24086482, 2013). "Chromatin immunoprecipitation with GLI1 or GLI2 antibodies precipitated fragments of the hTERT promoter in human colon cancer cells, which was reduced upon exposure to GANT61." (PMID 24086482, 2013). "The relative potential of activating the other molecules between GLI1 and GLI2 was also measured and we found that GLI2 had higher number of downstream activated species in the colon cancer scenarios, as it had connection with GLI1." (PMID 23935937, 2013). "It is evident that the drivers of HH signaling, the GLI genes, are critical to the survival of human colon carcinoma cells, and that DNA damage signaling downstream of GLI1/GLI2 inhibition is a critical regulator of cell death." (PMID 23097684, 2012). "GANT61, and the classic SMO inhibitor cyclopamine (for comparison with other model systems), were evaluated in a panel of human colon carcinoma cell lines to determine the impact of inhibiting GLI1/GLI2 vs SMO." (PMID 21860067, 2011). "In summary, we have compared gene expression profiles in two human colon carcinoma cell lines after targeting the function of the transcriptional regulators of HH signaling, GLI1 and GLI2, using the small molecule inhibitor GANT61." (PMID 20957031, 2010). "Furthermore, in air liquid interface (ALI) organoids derived from patients with colon cancer, Hedgehog signal inhibitor reduced the resistance to 5-FU, Irinotecan and Oxaliplatin via the inhibition of GLI-1 expression." (PMID 32503256, 2020). "We extended our study to determine whether LTC4-induced 15-PGDH affected stemness in colon cancer cells as well as the possible role of GLI1." (PMID 32814764, 2020). "To determine whether LTC4 acts via CysLT2R, as LTC4 is the high-affinity ligand of CysLT2R, we investigated the specific involvement of CysLT2R signalling in the LTC4-mediated downregulation of GLI1 in colon cancer cells." (PMID 32814764, 2020). "Starting from these observations, we investigated the putative effect of ST8176AA1-mediated epigenetic modulation on the Sonic hedgehog (Hh) signaling pathway and, in particular, on Gli1 transcriptional activity, in colon carcinoma cells where activation of this pathway plays a relevant role." (PMID 32039017, 2019). "In addition, other components of Hh signaling, such as SHH and GLI1, were also reported as being upregulated in colon cancer." (PMID 30423843, 2018). "Therefore, it was clear that the abnormal activation of GLI proteins in colon cancer cell lines not only happened due to the abnormal expression of hedgehog ligands but also due to the effect of the interactions of RAS with GLI1 and GLI2." (PMID 23935937, 2013). "To identify unique downstream targets of the GLI genes that function in cellular proliferation in the context of colon carcinoma, we employed a small molecule inhibitor of both GLI1 and GLI2, GANT61, identified in a cell-based small molecule screen for inhibitors of GLI1-mediated transcription." (PMID 20957031, 2010). "To identify unique downstream targets of the GLI genes, the transcriptional regulators of HH signaling, in the context of colon carcinoma, we employed a small molecule inhibitor of both GLI1 and GLI2, GANT61, in two human colon cancer cell lines, HT29 and GC3/c1." (PMID 20957031, 2010). "Likewise, SHH signalling dysregulation has been reported to contribute to metastasis and angiogenesis in colon cancer, and termination of SHH signalling through glioma-associated oncogene (GLI1) inhibition resulted in the inhibition of proliferation in colon cancer." (PMID 36701089, 2023).
colon carcinoma (continued). "Therefore, the LTC4/CysLT2R/15-PGDH signalling-mediated downregulation of Hh–GLI1 signalling combined with increased redifferentiation could be an alternative therapeutic treatment in addition to classical chemotherapy for colon cancer patients." (PMID 32814764, 2020). "The same is true for colon cancer cells, where SHH and GLI1 expression are increased after irradiation and contribute to tumor repopulation after radiotherapy." (PMID 38731849, 2024). "On the other hand, several studies in colon cancer show that the canonical Hedgehog pathway inhibits Wnt by regulating the expression of SFRP1 via its effector proteins, GLI1 and GLI2." (PMID 38474826, 2024). "Researches indicated that CNIH4 potentially increases colon cancer cell metastatic activity by forming a positive feedback loop with TMED9, GLI1, and TGFα." (PMID 37062068, 2023). "A relevant study confirmed that CNIH4 increased the metastatic activity in patients with colon cancer by forming a positive feedback loop involving TMED9, GLI1, and TGFα." (PMID 37062068, 2023). "Similar results are observed when a small molecule inhibitor of GLI1 and GLI2, GANT61, was used to block HH signalling in human colon carcinoma cell lines that express HH signalling components." (PMID 34445078, 2021). "In the same study, the authors found that GLI1 and GLI2 expression from a data microarray from a cohort of 382 colon cancer patients were strongly correlated with reduced OS and disease-free survival (DFS)." (PMID 34572373, 2021). "We observed that GLI1 was involved in the regulation of the redifferentiation and reduction in stemness induced by LTC4 via 15-PGDH in colon cancer cells." (PMID 32814764, 2020). "To elucidate the regulatory activity of GLI1 on the antitumorigenic proteins CysLT2R and 15-PGDH and the differentiation marker Mucin-2 in colon cancer, we used a tissue microarray (TMA) of primary CRCs from 326 patients." (PMID 32814764, 2020). "To confirm the involvement of the SHH and Notch signaling pathways in physciosporin-induced reduction of colon cancer cells, we subjected CSC221 cells overexpressing Gli1/2 and/or ΔEN1 to spheroid assays with exposure to physciosporin for 14 days." (PMID 31795147, 2019). "It has been reported that Hh signaling is blocked more efficiently by GANT61 at the level of GLI1/GLI2, which in turn induces DNA damage and cell death in human colon carcinoma cells, compared with the SMO inhibitor cyclopamine." (PMID 27349387, 2016). "Together with the marked overall downregulation of GLI1 and HHIP, these results provide consistent evidence that stromal downstream Hh activity is diminished in colon cancer." (PMID 27492255, 2016). "GLI1 inhibition by continuous exposure to pharmacological inhibitor GANT61 for 48 h induced DNA damage and extensive cell death in colon cancer cells." (PMID 26633513, 2015). "Blocking GLI1/2 activity reduced hTERT mRNA expression and the direct interaction between GLI1/GLI2 proteins and the hTERT promoter in human colon cancer cells." (PMID 24086482, 2013). "Exogenous expression of GLI1 or GLI2 increased hTERT mRNA and protein expressions and hTERT promoter-luciferase activity in human colon cancer cells." (PMID 24086482, 2013). "Transient expression of GLI3R repressed GLI1 and GLI2 transcriptional activity in colon cancer cell lines, paralleling the effects of GANT61." (PMID 23097684, 2012). "Inhibition of GLI1 and GLI2 by GANT61 induced > 80% cell death in 5/7 human colon carcinoma cell lines following 72 hr exposure (20 μM)." (PMID 21860067, 2011).